KRAS (KRas proto-oncogene, GTPase)
Diseases named in the same sentence as KRAS in open-access papers (continued):
Sharing a sentence is not in itself a finding about the gene and the disease.
tumor (continued). "Tumor dynamics obtained from KRAS monitoring could provide important information about treatment strategies for patients with mCRC, such as detection of drug resistance to anti-EGFR antibody before radiographic documentation of disease progression." (PMID 29849949, 2018). "These fibroblast cultures derived from tumor tissues expressed Vimentin and harbored no KRAS mutation as did the patient’s tumor, distinguishing them from epithelial tumor cells." (PMID 29587663, 2018). "Finally, genetic knockdown of MAPK7 combined with the MEK inhibitor cobimetinib in a mutant KRAS NSCLC xenograft model to mediate improved tumor growth inhibition." (PMID 29912950, 2018). "Hence we show that mutant KRAS facilitates IKKα-mediated responsiveness of tumor cells to host IL-1β, thereby establishing a host-to-tumor signaling circuit that culminates in inflammatory MPE development and drug resistance." (PMID 29445180, 2018). "Zhang and colleagues evaluated the anti-tumor effect of an anti-KRAS ribozyme adenoviral vector (KRbz-ADV) in NSCLC cell lines with or without KRAS mutation, finding that KRbz-ADV inhibits significantly the growth of KRAS mutant than wild type cells." (PMID 29464099, 2018). "It was also found to regulate KRAS to suppress tumor cell invasion and migration." (PMID 29785186, 2018). "It should be highlighted that the LOD of Sanger sequencing for mutations of both BRAF and KRAS genes at their laboratory and the estimation of tumor cell percentage were not mentioned." (PMID 29879227, 2018). "Since MDA-MB-231 and SUM-159 have activating mutations in KRAS and HRAS respectively, it is possible that GADD45A could be functioning as a tumor suppressor in these cell lines." (PMID 28235006, 2017). "Accordingly, only a fraction of CRIS-A samples had a high L score, and this class received additional samples from CMS3, encompassing tumours with mixed MSI status, enrichment for KRAS mutations, and metabolic deregulation, but devoid of intense leukocyte infiltration." (PMID 28561063, 2017). "SHR8443 was well tolerated when administered orally and displayed broader and stronger antitumor activity than BEZ235 against tumor xenografts formed from PTEN-null U-87MG and PC-3 cells, KRAS-mutated A549 cells, PI3K-mutated BT-474 cells, and trastuzumab-resistant BT-474/trastuzumab cells." (PMID 29296217, 2017). "Total cfDNA concentrations of patients carrying KRAS mutations showed higher increases after the resection than cfDNA of WT tumour or control patients, independent of the initial cfDNA concentrations." (PMID 28827745, 2017). "We performed validation of the QIAGEN GeneReader NGS System using the QIAact Actionable Insights Tumor Panel, focusing on clinically meaningful mutations by using DNA extracted from formalin-fixed paraffin-embedded (FFPE) colorectal tissue with known KRAS mutations." (PMID 28532404, 2017). "It would also be interesting in future studies to evaluate the correlation between ctDNA KRAS and tumor load or shrinkage, as well as whether the depth of decrease of KRAS ctDNA from baseline could be predictive for survival." (PMID 29228650, 2017).
tumor (continued). "Likewise, many studies supported the role of the nuclear transcription factor yes-associated protein 1 (YAP1) in compensating cancer cell survival and proliferation in KRAS-independent neoplasms, including PDAC." (PMID 28895920, 2017). "While KRAS is a common oncogene in lung ADC, LKB1/STK11, encoding a serine-threonine kinase implicated in energy sensing and cell polarity, is notable as being among the most commonly mutated tumour suppressors in ADC2." (PMID 28387316, 2017). "Therefore, this manuscript focuses on 411 patients (309 LPT, 102 RPT) with KRAS exon 2 wild-type mCRC, documented second-line therapy and available information on primary tumor location." (PMID 29285289, 2017). "EGFR and KRAS mutation, expression of EGFR family members and of cMET and PTEN and EGFR and ABCG2 germline polymorphisms were tested on tumor tissue or blood samples to either confirm previously proposed predictive role or describe it in an explorative setting." (PMID 28915692, 2017). "Routinely, KRAS status is based on the analysis of the usual FFPE tumour sample." (PMID 28234922, 2017). "PD-1 blocker or ERK inhibitor could recover the anti-tumor immunity of T cells and decrease the survival rates of KRAS-mutant NSCLC cells in co-culture system in vitro." (PMID 28451792, 2017). "The concomitant occurrence of KRAS and BRAF mutations is very rare in CRCs (< 1%), which imply tha they may play a role in different tumor subtypes." (PMID 28583095, 2017). "KRAS vaccine significantly decreased surface tumors from ∼150 tumors per mouse lung in non-vaccinated mice to ∼21 tumors in vaccinated mice, and decreased tumor volume nearly 90% (19.1mm3 to 2.4mm3)." (PMID 29137294, 2017). "CRIS-A is highly enriched for BRAF-mutated MSI tumours and KRAS-mutated MSS tumours, for which no targeted treatment options are currently available." (PMID 28561063, 2017). "In a retrospective analysis of the PEAK, FIRE-3, and CALGB/SWOG80405 trials, this trend was also apparent when including subjects with any RAS tumor mutation, rather than just those with KRAS exon 2 tumor mutations." (PMID 28068936, 2017). "Furthermore, we have determined that miR-217 is downregulated in PDAC and functions as a tumour suppressor gene by inhibiting KRAS translation." (PMID 28701723, 2017). "In one patient, the KRAS status was discordant between the primary tumor and CTCs." (PMID 28468669, 2017). "Given the high frequency of KRAS mutations in PDA of over 90% in most reports, we can use this specific genomic alteration as a gold standard to gauge technical utility, which provides a unique window into cfDNA-tumor tissue concordances." (PMID 29137355, 2017). "The current label for panitumumab includes a contraindication for its use in combination with oxaliplatin-containing chemotherapy in patients with mutant or unknown RAS tumour status (or KRAS status before June 2013)." (PMID 29183279, 2017). "This may explain why the development of KRAS-driven cancers is strongly aided by elements of the tumor microenvironment, including growth factors and cytokines." (PMID 28152508, 2017). "Six PDXs, representing 20.8% of the tumours in this study, harboured druggable somatic mutations, including PIK3CA p.H1047R and KRAS p.A146V in WHIM9, PIK3CA p.H1047R in WHIM16 and WHIM24, PIK3CA p.E545K in WHIM18, PIK3CA p.E542K in WHIM20 and SF3B1 p.K700E in WHIM26." (PMID 28348404, 2017). "Importantly, RT11-i markedly inhibited the growth of the three oncogenic KRas mutant tumour xenografts, showing ∼46–70% more tumour-growth inhibition (TGI) and ∼42–63% greater reduction in tumour weight, compared to those after treatment with TMab4-i." (PMID 28489072, 2017).
tumor (continued). "In consideration of tumor heterogeneity, we have not found KRAS, CDKN2A or SMAD4 mutations in our samples." (PMID 28008139, 2017). "Oncogenic KRAS drives metabolic reprogramming in tumor cells by increasing aerobic glycolysis, and recent studies showed that subtypes of PDAC cells with distinct metabolite levels associated with glycolysis, lipogenesis, and redox pathways, confirmed at the transcriptional level." (PMID 28061880, 2017). "Cells from this individual were chosen because there is a KRAS mutation in tumor cell line HCC4017 while there is no KRAS mutation in HBEC30-KT and HBEC30-UI cells." (PMID 28052041, 2017). "An improved understanding of the biology and signalling that support KRAS-mediated resistance may therefore give rise to new therapeutic strategies for these refractory tumours." (PMID 28593995, 2017). "Pembrolizumab or ERK inhibitor could recover the anti-tumor immunity of T cells and decrease the survival rates of KRAS-mutant NSCLC cells in co-culture system in vitro." (PMID 28451792, 2017). "We finally explored whether this effect on cell growth in the in vitro 3D cultures and KRAS activation could be translated to an increase in xenograft tumour growth in vivo." (PMID 28692044, 2017). "Importantly, in vivo tumour growth 22 days post-implant was significantly greater in tumours derived from mutant KRAS -PDHK4 stable clones 1 and 7 than in the empty vector clone." (PMID 28692044, 2017). "Other experiments suggest that ERH underexpression may constrain tumor aggressiveness, given that ERH knockdown reduces tumor cell viability through KRAS oncogene-dependent pathways." (PMID 28719635, 2017). "Comparison of clinicopathological features between patient subgroups with or without detectable plasma tumor-specific KRAS mutations within the metastasis group (n = 106)." (PMID 28459822, 2017). "In 10 of 11 patients, the KRAS status was the same in the primary tumor and CTCs." (PMID 28468669, 2017). "One patient with a KRAS codon 12 mutation in the tumor but showing no detectable RAS mutation in plasma had a normal CEA concentration (2.4 ng·mL−1)." (PMID 28106345, 2017). "In conclusion, ICIs as a salvage therapy improved overall survival over that with docetaxel in advanced NSCLC patients with KRAS mutation, but not in those with KRAS wild-type tumor." (PMID 28525386, 2017). "The combination of cetuximab and PBR extract produced a statistically significant reduction in tumor volume, compared with that of cetuximab alone, in the KRAS-mutant SW480 xenografts (mean tumor volume on day 26 = 3344 ± 572 mm3 vs. 1870 ± 571 mm3, cetuximab vs. cetuximab + PBR, p = 0.011)." (PMID 28800074, 2017). "Additionally, tumours and cell lines with NF1 lesions were found to lack KRAS and BRAF mutations, whilst exhibiting Ras pathway activation." (PMID 28637487, 2017). "Finally, CRIS-E aggregates KRAS-mutated, Paneth cell-like CIN tumours that are refractory to treatment with anti-EGFR antibodies." (PMID 28561063, 2017). "Here, we started the vaccination before KRAS activation in an inducible CCSP-KRAS murine model, where the vaccination was given before cancer development and thus, theoretically, in the absence of tumor-associated immunesuppression." (PMID 29137294, 2017). "In a portion of such cases of multiclonal initiation, a PIK3CA or KRAS mutant cell may acquire an additional genetic hit and progress to become the predominant tumor clone." (PMID 28755461, 2017).
tumor (continued). "We found that Pembrolizumab could re-activate the anti-tumor immunity of T cells and decrease the survival rates of NSCLC cells with endogenous KRAS mutation in co-culture system." (PMID 28451792, 2017). "Therefore, we conclude that STK38L and KRAS function in parallel pathways to promote tumor cell survival." (PMID 29108249, 2017). "The same approach was used by other investigators reporting the identification of the X-linked deubiquitinase USP9X as the gene most frequently mutated in KRAS mice submitted to insertional mutagenesis: loss of USP9X gene enhances transformation and promotes tumor progression." (PMID 29156578, 2017). "Despite the heterogeneity of the sample, pooled results suggest that KRAS mutations act as a negative predictive marker for tumor response in NSCLC patients treated with anti-EGFR therapies." (PMID 29285236, 2017). "Negative conversions of KRAS mutations were observed in 4 patients whose tumor burdens were significantly reduced (data not shown)." (PMID 28459822, 2017). "The paper showed that some mutations in relevant genes (APC, KRAS, PI3KCA), previously found only in CTCs, could be uncovered at subclonal level also in the main tumor and in metastases of the same patient, thanks to the use of specific algorithms." (PMID 29221448, 2017). "On contrary, the levels of cfDNA mutations in patients without a prior KRAS/NRAS/BRAF/PIK3CA tumor mutation were 10-fold lower than the mutation cutoff (p = 0.002)." (PMID 27852040, 2017). "Five of the six KRAS mutant tumours were in the left colon, sigmoid colon or rectum." (PMID 28097409, 2017). "Besides the NLR right side tumor location in KRAS wildtype patients appeared to be a strong predictor of limited chemotherapy response." (PMID 29221186, 2017). "For both patients, we sequenced the KRAS gene in primary tumor samples." (PMID 29156783, 2017). "Mutant KRAS tumours undergo a high degree of mitotic stress and, thus, genes contributing to this phenotype may represent cancer vulnerabilities." (PMID 28220783, 2017). "Hence, extended RAS testing of tumor tissue (primary or metastatic) beyond KRAS exon 2 is now recommended both by the European Society of Medical Oncology (ESMO) and by the National Comprehensive Cancer Network (NCCN)." (PMID 28201998, 2017). "Several previous reports have tried to identify predictive markers of response to nCRT, with some finding that pCR was associated with good tumor differentiation, a small tumor diameter, early T and N stage on imaging, low levels of pretreatment CEA and KRAS mutations." (PMID 29108299, 2017). "A later analysis of one of the very small tumours of the lower lobe (not of relevance for the clinical handling of the patient) revealed the same KRAS mutation while the SMAD4 mutation was not seen." (PMID 28347348, 2017). "We agree it is difficult to draw certain conclusions given the evidence of today, though in our opinion, different driver mutations (such as EGFR or KRAS mutations or ALK or ROS1 rearrangements, like in our cases 4 and 6) probably quite strongly support synchronous/metachronous tumours." (PMID 28347348, 2017). "Previous concordance studies of SOC FFPE KRAS mutation detection assays showed minimal variation in the presence or absence of KRAS mutations, most likely due to differential tumor cell selection from formalin‐fixed tumor tissue." (PMID 28106345, 2017). "The KL mouse model, as well as SqCC cell line HCC1588, features a KRAS mutation whose role in driving SqCC tumour formation is not well understood." (PMID 28548087, 2017). "This suggests that the transcriptional response is highly dependent on the tissue of origin and raises the question whether a core of genes relevant for mutant KRAS biology is preserved across different tumour types." (PMID 28220783, 2017).
tumor (continued). "It is possible that the discordance between primary tumor and CTC could account for the failure of anti-EGFR therapy in patients with KRASWT tumors, who in fact harbor KRAS mutations in their CTC." (PMID 28674438, 2017). "Importantly, KRAS inhibition alone was insufficient to maintain tumor growth suppression, possibly due to selection of escapers harboring non-frameshift mutations and/or cells that bypassed the requirement of KRAS by PI3K/AKT activation." (PMID 29061961, 2017). "Taken together, miR-181a plays a crucial tumor suppressive role in SCC by targeting KRAS and could be a promising candidate for a miRNA based therapy." (PMID 28931048, 2017). "The prognostic importance of activating KRAS mutations extends beyond predicting sensitivity to anti-EGFR monoclonal antibodies, and may reflect a more migratory and invasive tumor biology resulting in early and frequent recurrences after hepatic resection." (PMID 29108374, 2017). "However, determining the actual tumor dependency on mutant KRAS for survival from such genetic data is difficult and in vivo validation is required by taking into account for KRAS dependency." (PMID 28173629, 2017). "Moreover, the survival and genetic data were recapitulated in PDAC, what supports the analysis across different tumour types to unveil common KRAS targets." (PMID 28220783, 2017). "This correlation may be due to the ability of KRAS mut tumors to metastasize more readily or also could be due to resistance to radiation-induced apoptosis present in these tumor cells." (PMID 28415671, 2017). "However, we did not detect an increased proliferative or clonogenic capacity specifically characterizing KRAS-mutant cells and tumours compared with KRAS-wild-type ones." (PMID 28508873, 2017). "We report on the utilization of a novel mutant allele enrichment ctDNA assay in patients with advanced PDA yielding a circulating tumor DNA (ctDNA) KRAS baseline detection rate of 93.7% (95% CI 89.2%–96.7%), outperforming the detection rate of prior reported assays." (PMID 29228650, 2017). "Moreover, stable expression of PDHK4 increased localization of activated KRAS at the plasma membrane and induced tumour cell growth in vitro and in vivo." (PMID 28692044, 2017). "Recent studies showed the detection of clinically relevant oncologic driver mutations like e.g. KRAS, EGFR or secondary EGFR T790M resistance mutations in ctDNA with nearly maximal specificity (> 95%) compared to tumor tissue as the gold standard in cancer diagnostics." (PMID 29156792, 2017). "Irrespective of LKB1 status, phenformin may enhance the anti-tumor effect of selumetinib in KRAS-mutant NSCLC." (PMID 28938614, 2017). "It is therefore likely that TRAIL and its function as a promoter of a tumor-supportive immune microenvironment may also play a role in this KRAS-induced genetic model." (PMID 28212753, 2017). "At the time of first diagnosis, tumor tissue obtained from an open regional lymph node biopsy showed a poorly differentiated adenocarcinoma with a wild type sequence within exon 2 (codon 12/13) of the KRAS gene." (PMID 28549417, 2017). "The identification of FOSL1 through a cross-tumours approach including LAC, PDAC, CRC, CCA and MM suggested that it could be relevant in other KRAS-driven tumours." (PMID 28220783, 2017). "As a control, the HCC4087 tumor cell line established using non-CRC condition had a KRAS mutant allele frequency of 67%." (PMID 28052041, 2017). "Primer-extension mass spectrometry genotyping of the tumor revealed a KRAS G12C mutation, and immunohistochemistry showed no PD-L1 expression in tumor cells." (PMID 28716137, 2017).